CD68 (CD68 molecule)
Diseases named in the same sentence as CD68 in open-access papers (continued):
Sharing a sentence is not in itself a finding about the gene and the disease.
epilepsy (8 papers, 2020 to 2026). A brain disorder characterized by episodes of abnormally increased neuronal discharge resulting in transient episodes of sensory or motor neurological dysfunction, or psychic dysfunction. "These morphologically microglia-like cells, both CD68-positive and Iba1-positive, were still detectable 7 weeks after SE during the chronic epilepsy phase, notably in CA1." (PMID 41445743, 2025). "To this end, we analyzed the transcript levels of the inflammasome mediators Il1β, Il6, Il12, Il10, Tnfα, Cd68, Ccl2, and Ccl5, which are upregulated in pilocarpine‐ and kainic acid‐induced epilepsy models." (PMID 40608247, 2025). "The mRNA level of Cd68 and Tyrobp was also significantly up‐regulated in the latent stage after epilepsy in the current study." (PMID 33225612, 2020). "Only a few CD68-positive round cells were detected 7 weeks after SE, once epilepsy was established." (PMID 41445743, 2025). "CD68 was the highest in rats in the epilepsy group and was statistically significant." (PMID 35493845, 2022). "At the tissue level, the downregulation of the TLR4/NF-κB inflammatory pathway in epilepsy inhibited microglial activation and CD68 expression, inhibited hyperphagocytosis, inhibited the occurrence and exacerbation of epilepsy, and thus improved cognitive and emotional behavior after epilepsy." (PMID 35493845, 2022). "Immunofluorescence staining for CD68 and Iba1 revealed increased microglial activation in the PBS-treated epilepsy group, which was significantly attenuated following L. eligens administration, indicating suppression of neuroinflammatory microglial responses." (PMID 41356796, 2026). "We showed that CBD significantly reduces the transcript levels of the proinflammatory immune biomarkers IL‐12, CD68, CCL2, and IRF3, found previously upregulated in rodent models of induced epilepsy and in pediatric patients with encephalopathy." (PMID 40608247, 2025). "Rather, quantification of CD68 and GAD65 immunofluorescent signals within IBA1+ microglia indicated a preference for pruning inhibitory synapses during KA‐induced epilepsy." (PMID 37072932, 2023). "Then, we measured the levels of Arg-1, CD68, iNOS and CD86 in the hippocampus 24 hours after epilepsy modeling." (PMID 35356535, 2022).
head and neck squamous cell carcinoma (8 papers, 2009 to 2025). A squamous cell carcinoma that arises from any of the following anatomic sites: lip and oral cavity, nasal cavity, paranasal sinuses, pharynx, larynx, and salivary glands. "An additional study showed a prognostic significance between CD68+ and CD163+ in head and neck squamous cell carcinoma, and they found that CD68+ has no prognosis in patients, whereas CD163+ predicts poor prognosis." (PMID 36982316, 2023).
histiocytic sarcoma (8 papers, 2012 to 2026). An aggressive malignant neoplasm with a poor response to therapy, usually presenting as stage III/IV disease. "Previously, immunohistochemical markers used for histiocytic sarcomas in rats included vimentin, CD68 and lysozyme." (PMID 35454212, 2022). "Histiocytic sarcoma (HS) is an uncommon malignant neoplasm arising from mature histiocytes and most commonly characterized by the immunophenotypic expression of CD68, CD163, or lysozyme." (PMID 31687231, 2019). "Immunohistochemistry tests confirmed the cells were of histiocytic origin, strongly expressing CD68, CD163, LCA, and S100, confirming the diagnosis of histiocytic sarcoma." (PMID 42256916, 2026). "In immunohistochemistry, these atypical cells were specifically positive for CD68 (KP-1), CD163, and lysozyme, which was consistent with histiocytic sarcoma (HS) of the spleen." (PMID 23075171, 2012). "Still, immunohistochemistry of histiocytic sarcoma shows the expressions of histiocytic markers, including CD68, CD163 and lysozyme, with the absence of B‐cell, T‐cell, dendritic cell, epithelioid cell, myeloid cell markers." (PMID 38450981, 2024). "Histiocytic sarcoma (HS) is an extremely rare hematopoietic neoplasm that originates from the macrophage lineage and shows a sarcoma‐like spread of CD4+, CD68+, PU.1+, and CD163+ histiocytic cells." (PMID 40938275, 2025).
inflammatory bowel disease (8 papers, 2017 to 2025). A spectrum of small and large bowel inflammatory diseases of unknown etiology. "A previous report described CD68-positive neutrophils in the colon mucosal tissue of patients with inflammatory bowel disease." (PMID 36530874, 2022). "CD68, a selective marker for monocytes and macrophages, have been previously connected to inflammatory diseases, like inflammatory bowel disease or Crohn's disease." (PMID 29228712, 2017). "Additionally, CD68+ macrophages, which are significant sources of inflammatory cytokines in inflammatory bowel disease (IBD)." (PMID 38835771, 2024). "For example, GPR109A is upregulated in inflammatory bowel disease (IBD) patient epithelia and lamina propria macrophages (CD68+)." (PMID 40787446, 2025). "In inflammatory bowel disease (IBD), aberrant macrophages (enriched for CD68+ and CD14hiCD16+ phenotypes) in the inflamed intestine promote cytokine production and delayed bacterial clearance, thereby promoting tissue injury and worsening disease outcome." (PMID 35323693, 2022).
Lipedema (8 papers, 2020 to 2025). Disorder of adipose tissue characterized by symmetric and bilateral enlargement of the lower extremities due to abnormal deposition of subcutaneous fat often in obese women. "Finally, evaluation of the macrophage infiltration using the marker CD68 revealed an increased macrophage presence in lipedema (C: 13 ± 2.8 cells/field, L: 21.2 ± 7.8 cells/field, P = 0.009) in comparison to the control." (PMID 32616854, 2020). "We treated the SVF from 5 lipedema and 5 control with 100 nM IPI-549 in vitro and analyzed the expression of CD163, CD206 and CD68." (PMID 36605202, 2022). "CD68‐positive macrophages were more abundant in affected areas compared with nonaffected areas in patients with lipedema, consistent with the increased adipocyte size in affected tissue." (PMID 40077894, 2025). "Interestingly, in areas of subdermal blood vessel networks and identified as CD31 positive and podoplanin negative, a higher number of macrophages (CD68+) is visible in lipedema skin, which may indicate blood vessels with altered permeability." (PMID 35625899, 2022). "Interestingly and in clear distinction to lipedema and secondary lymphedema, no increased immune cell infiltration was detected in lipohypertrophy, while the infiltration with CD4+, CD68+ or CD163+ cells was found comparable to the healthy controls." (PMID 37108757, 2023).
neuroblastoma (8 papers, 2013 to 2025). Neuroblastoma (NB) is the most common solid, extracranial childhood tumor. "Survival analysis further showed that high-risk neuroblastoma patients from Cohort 1 having tumors with both high CD68 and CD163 expression exhibited better survival." (PMID 35525858, 2022). "IHC staining of high-risk neuroblastoma tissues with anti-CD68 and anti-CD163 antibodies revealed that a number of macrophages positive for these markers were present in a similar density and distribution pattern." (PMID 35525858, 2022). "Furthermore, high-level co-expression of SLAMF7 and CD68 was significantly associated with better outcome of high-risk neuroblastoma patients." (PMID 35525858, 2022). "Furthermore, we found that high-risk primary neuroblastoma tumors contain CD68+ tumor-associated monocytes/macrophages (TAMs) producing IL-6 and that bone marrows with neuroblastoma metastases include CD33+ CD14+ monocytic cells, which also express IL-6." (PMID 23982484, 2013). "Consistent with the in vivo models and patient datasets, a significant increase in CD68 positive macrophages was identified in ATRX mutant neuroblastomas compared with MYCN-amplified or non MYCN-amplified disease." (PMID 39892705, 2025). "Moreover, IHC staining of serial sections from an unfavorable histology MYCN amplified neuroblastoma demonstrated that the majority of CD68+ macrophages co-expressed CD163." (PMID 35525858, 2022). "In addition, most macrophages co-expressing high levels of CD68 and CD163 could function as anti-tumor phagocytes in high-risk neuroblastomas at diagnosis." (PMID 35525858, 2022). "IHC labeling of the macrophage marker CD68 as well as double IF-P staining of CD68 and CMKLR1 in neuroblastoma tissue demonstrated that while the majority of CMKLR1 is expressed by the tumors cells, CD68+ cells in the TME also express CMKLR1." (PMID 29221117, 2017). "Interestingly, CD68-positive TAMs co-expressing IL-6 was identified in the metastatic bone marrow samples of non-MYCN-amplified neuroblastoma." (PMID 32983125, 2020). "In the neuroblastoma tissue itself, 10% of dendritic cells, no CD45 positive cells, 45% of CD11b positive cells, and no CD68 positive cells were found (for a summary of the results, and for a representation)." (PMID 33921688, 2021).
preeclampsia (8 papers, 2016 to 2024). Preeclampsia is a hypertensive disorder of pregnancy that is characterized by new-onset hypertension with proteinuria presenting after 20 weeks of gestation, and depending on mild or severe forms may initially present with severe headache, visual disturbances, and hyperreflexia. "Instead, we concluded that these are features of the decidual pathology of preeclampsia, while CD68+ foam cells are an essential aspect of acute atherosis." (PMID 34970270, 2021). "The ability of CD68 to bind to OxLDL may play a role in the development of foam cells, which have been observed in preeclampsia." (PMID 37269190, 2023). "Interestingly, endothelial MCP-1 is upregulated in preeclampsia, possibly due to atherogenic blood flow, and could possibly be involved in CD68+ cell recruitment to the sites of lesion development." (PMID 34970270, 2021). "The immunohistochemical study found more CD68+ monocytes/macrophages and myeloperoxidase (MPO)+ Granu in the placenta of the “immunological” preeclampsia subtype." (PMID 37854606, 2023). "An earlier study of patients with preeclampsia and preterm birth found a unique subset of CD14−/CD68+ cells in the placenta, and concluded that these cells were a subpopulation of macrophages based on their immunophenotypic characteristics." (PMID 34738274, 2022). "No significant findings have been detected, except from a trend toward higher placental CD68+ cells (P = 0.07) and HGF (P = 0.06) in preterm placentas and to higher CCL5 in patients with preeclampsia (P = 0.07)." (PMID 33313931, 2021).
rectal cancer (8 papers, 2020 to 2025). A primary or metastatic malignant neoplasm that affects the rectum. "The dense infiltration of the rectal cancer stroma with CD68+ macrophages has been linked with a favorable prognosis in colorectal cancer." (PMID 37232754, 2023). "The combination of intratumoral CLEVER-1+ lymphatic vesselhigh + CD68+ TAMlow was associated with poor DSS in stage I–IV rectal cancer." (PMID 34885098, 2021). "In this study, a low CD68+ macrophage number in combination with a high CLEVER-1+ LVD was associated with poor survival in rectal cancer." (PMID 34885098, 2021). "In stage I-IV rectal cancer patients, a high number of CLEVER-1+ lymphatic vessels in combination with a low number of CD68+ macrophages was associated with poor survival (log-rank p = 0.049)." (PMID 34885098, 2021). "Additionally, a study found TP production by CD68+ macrophages to be increased after irradiation in samples of rectal cancer patients as well as colon cancer cell lines." (PMID 37958298, 2023). "Importantly enhanced expression of iNOS+CD68+ and NOX2+CD68+ TAMs was observed in resected specimens of rectal cancer patients with good responses to neoadjuvant radiotherapy." (PMID 36249052, 2022). "mIHC was performed on tumour specimens obtained from patients diagnosed with gastric and rectal cancer, aiming to investigate the association between the expression levels of LOX and LOXL2 and the presence of CAFs expressing α‐SMA, as well as TAMs expressing CD68 and CD206." (PMID 40179101, 2025). "As a third case study, we applied SIMPLI to the spatial analysis of mIF-derived images of a rectal cancer sample (CRC1) stained with anti CD8, PD1, Ki67, PDL1, CD68, GzB and 4’,6-diamidino-2-phenylindole (DAPI) antibodies." (PMID 35140207, 2022).
sarcoidosis (8 papers, 2012 to 2024). Sarcoidosis is a multisystemic disorder of unknown cause characterized by the formation of immune granulomas in involved organs. "Altogether, human sarcoidosis skin granulomas are characterized by the presence of lipid-laden CD68+ macrophages with aberrant lipid metabolism." (PMID 38353578, 2024). "In sarcoidosis, GC shave been shown to be CD68-positive, pointing to their derivation from inflammatory macrophages; our data confirm this." (PMID 37509363, 2023). "Both the Langhans-type GCs of sarcoidosis and tuberculosis and the foreign body GCs are CD68-positive throughout." (PMID 37509363, 2023). "In contrast BAL-macrophages from sarcoidosis patients expressed higher CD68 positive cells than in BD (56.43% ± 9.8%; range 40 - 61.5; P = 0.0002)." (PMID 22330585, 2012). "In contrast sarcoidosis patients showed a higher expression of CD68-positive cells." (PMID 22330585, 2012). "Because sarcoidosis is notably associated with Th1/Th17 multisystem abnormity, an increased number of CD68+ CD163− M1 macrophages and CD209+ dendritic cells and a decreased number of CD68+ CD163+ M2 macrophages may be a histologic surrogate for the diagnosis of cardiac sarcoidosis." (PMID 35011991, 2022). "Interestingly, we found a CD68+ F4/80+ (Adgre1) macrophage population in the skin of Tsc2KO sarcoidosis mice that was not present in Tsc2WT mice." (PMID 38353578, 2024).
acute myeloid leukemia (7 papers, 2018 to 2025). Acute myeloid leukemia (AML) is a group of neoplasms arising from precursor cells committed to the myeloid cell-line differentiation. "In acute myeloid leukemia, high CD163 expression has been linked to shorter survival, whereas CD68 showed no prognostic correlation." (PMID 41239536, 2025). "In this case, CD21 and CD35 were positive and CD45 was weakly positive; T and B cell markers were negative; MPO was positive, but CD117, CD15, and CD68 were negative; therefore, myeloid sarcoma and acute myeloid leukemia were not considered." (PMID 37833728, 2023).
aortic aneurysm (7 papers, 2020 to 2024). A ruptured aneurysm located in the wall of the proximal portion of the descending aorta proceeding from the arch of the aorta. "The relative expression level of the contractile marker ACTA2 decreased to 0.307 (p < 0.001) in the aortic aneurysm model, while the expression level of CD68 increased to 54.85 (p < 0.001)." (PMID 37189183, 2023). "Abundant infiltration by CD68-positive macrophages was detected in the adventitia and media of the aortic aneurysms from the AngII-infused mice." (PMID 32362823, 2020). "Interestingly, we found cells expressing both CB1R and resistin in the CD68-positive area of the atheromatous plaque of aortas obtained from patients with aortic aneurysm." (PMID 39050819, 2024). "Biopsy samples of 11 patients with aortic aneurysm were immunomorphologically examined using antibodies to Lp(a) and CD3, as well as antibodies to CD4, CD8, and CD68." (PMID 33023269, 2020). "Macrophage-like VSMCs (αSMA + CD68+) were observed in the tunica media of aortic aneurysms but were not fund in the normal aorta." (PMID 35837612, 2022). "However, at more advanced stage, most of CD68+ macrophages in Jak2V617FHC-EC mice with severe aortic aneurysm did not colocalize with LYVE-1+ staining." (PMID 36329047, 2022).
cardiac hypertrophy (7 papers, 2020 to 2025). "In our study we infused angiotensin II for ~ 6 weeks, inducing cardiac hypertrophy, albuminuria, CD68 + monocyte/macrophage infiltration and perivascular fibrosis." (PMID 38670993, 2024). "PCH mice had excessive myocardial hypertrophy, fibrosis, and aggravated LVSD, which were accompanied by massive CD68+ inflammatory cell infiltrations." (PMID 34631707, 2021). "In particular, enhancement of TLR4 signaling has been reported to trigger ROS production, inflammation and CD68+ macrophage infiltration, leading to cardiac hypertrophy, fibrosis and HF, whereas administration of TLR4 antagonist prevented cardiac hypertrophy and dysfunction." (PMID 36012897, 2022).
cyst (7 papers, 2009 to 2026). A sac-like closed membranous structure that may be empty or contain fluid or amorphous material. "In cyst content cases with epithelioid, poorly preserved or atypical macrophages, histiocytic markers, such as CD68, can confirm their identity and help prevent an atypical diagnosis." (PMID 35092649, 2022). "Notably,differentiation of OSE cells in EICs through Müllerian pathways isassociated with the presence of monocyte derived CD68 positive cells (MDC) thatinfiltrate the cyst wall and accumulate in the cyst lumen (arrows, Figure 9Aand B)." (PMID 20195382, 2009). "Results achieved by the current study also confirmed that CD68+ MΦ and MPO+ neutrophils weakly infiltrate the liver parenchyma surrounding the cyst in chronic infection." (PMID 26578348, 2015).
dysplasia (7 papers, 2015 to 2023). A usually neoplastic transformation of the cell, associated with altered architectural tissue patterns. "The infiltration of CD8-positive T cells and CD68-positive macrophages in HLA-I-high dysplasia/CC was significantly higher than in UC and SCRC." (PMID 37686454, 2023). "In cervical and oropharyngeal cancer, for example, high infiltration by CD163+ and CD68+ macrophages was correlated with the tumor progression from normal tissue to dysplasia to carcinoma." (PMID 34194435, 2021). "If we consider the stromal compartment, we observed a higher number of CD68+ macrophages in the stromal region of carcinoma than in the stromal region under dysplasia, and these differences were statistically significant." (PMID 29541395, 2018). "We observed increases of CD4+ T-cells, Foxp3+ T-lymphocytes, CD68+ macrophages, and IL-4+ cells during the progression of dysplasia in OLK and a parallel decrease in the expression of the inflammatory cytokine IFN-γ." (PMID 28053372, 2016). "The percentage of CD68+ macrophages increased sequentially from the normal mucosa to inflammatory hyperplasia, dysplasia, and carcinoma transition in the mice of the AOM/DSS group." (PMID 25434400, 2015). "Moreover, the infiltration of CD8-positive T cells and CD68-positive macrophages in dysplasia/CC tissues with high HLA-I levels was significantly higher than that in UC and SCRC tissues." (PMID 37686454, 2023). "In conclusion, this study revealed that dysplasia/CC specimens with DNA damage exhibited high levels of membrane HLA-I-positive epithelial cells with high CD8- and CD68-positive immune cell infiltration compared to UC and SCRC specimens." (PMID 37686454, 2023). "Dysplasia/CC specimens with DNA damage exhibited high levels of HLA-I-positive epithelial cells with high CD8- and CD68-positive immune cell infiltration compared to UC and SCRC specimens." (PMID 37686454, 2023). "We performed immunohistochemical staining for HLA-I, PD-L1, γH2AX (DNA damage marker), and immune cell markers such as CD8, FOXP3, CD68, and CD163 (in surgically resected specimens from 17 SCRC patients with 12 adjacent normal mucosa (NM) and 9 UC patients with 18 dysplasia/CC tumors." (PMID 37686454, 2023). "Increased infiltration of macrophages was observed in the entire colon of CAC mice including the relatively non-inflamed and non-dysplasia portions, as evidenced by an increased CD68 and MR staining." (PMID 26799669, 2016). "The number of infiltrating immune cells with CD8 and CD68 expression in dysplasia/CC with high HLA-I levels was higher than that in UC and SCRC; however, this was not significant in dysplasia/CC with low CD8 infiltrating immune cells." (PMID 37686454, 2023).